SMAD4 (SMAD family member 4)
Diseases named in the same sentence as SMAD4 in open-access papers (continued):
Sharing a sentence is not in itself a finding about the gene and the disease.
pancreatic cancer (continued). "In a SMAD4 knockout pancreatic cancer cell line, the nanoS/MAR was found to drive higher transgene expression and elicit minimal changes in gene expression related to immune pathways." (PMID 37337429, 2023). "The two most common genetic alterations in pancreatic cancer are mutations in the Kirsten rat sarcoma viral (KRAS) oncogene and inactivation of SMAD4." (PMID 36902253, 2023). "We found that S100A2 affects cell metastasis and EMT in pancreatic cancer by regulating SMAD4 via the TGF-β/Smad pathway." (PMID 37758734, 2023). "In pancreatic cancer, HNF4G was also found to be induced by SMAD4 deficiency, promoting progression and metastasis but being suppressed by the metformin/APMK signaling pathway." (PMID 36923501, 2023). "SMAD4, a downstream of β-catenin, is overexpressed in various types of cancer, and deleting the SMAD4 gene has protective effects against pancreatic cancer." (PMID 37265908, 2023). "In 30% of pancreatic cancers, SMAD4 is deleted following inactivation of K-ras, increasing TGF-β expression and creating an environment for tumour progression." (PMID 38066625, 2023). "This was also the case for SMAD4 in pancreatic cancer, TBX3 in colorectal cancer, or TSC2 in liver cancer." (PMID 36937541, 2023). "Comparable biological tendency was observed in pancreatic tumors, in which a decrease of RAB10 expression level seemed to be associated with a gain of SMAD4." (PMID 37377893, 2023).
pancreatic cancer (continued). "SMAD4’s role in cancer was first discovered in 1996, where SMAD4 gene alterations were shown to be closely related to pancreatic cancer." (PMID 36900240, 2023). "In colorectal and pancreatic cancers, the TGF-β signalling pathway is frequently abolished by mutations in SMAD4 or TGFBR2 (Massagué, 2008; Levy and Hill, 2006)." (PMID 37439249, 2023). "RHOT1 as an oncogene regulated the proliferation and migration of pancreas cancer cells via SMAD4-dependent TGF-β signaling." (PMID 35170374, 2022). "Taken together, we demonstrated the synergism of gemcitabine and DTLL in both gemcitabine-sensitive and gemcitabine-resistant PDAC and identified the critical role of SMAD4 in mediating the cellular responses of pancreatic cancer to chemotherapy." (PMID 36127339, 2022). "SMAD4 alterations are relatively specific to gastrointestinal cancers, notably pancreatic cancer, where SMAD4 is inactivated in 50–55% of cases." (PMID 35205719, 2022). "One study suggested that WWOX suppresses pancreatic cancer by upregulating SMAD4 signaling in Panc1 cells." (PMID 36572673, 2022). "Fifty SMAD4‐negative and 39 SMAD4‐positive pancreatic cancer patients were identified by IHC staining for SMAD4 expression." (PMID 35064757, 2022).
pancreatic cancer (continued). "Among the most frequently altered genes in PDAC is SMAD4, a tumor suppressor dispensable for normal pancreas development but critical for pancreatic cancer progression." (PMID 35155243, 2022). "SMAD4 also known as DPC4 (deleted in pancreatic cancer) is a well-known tumor suppressor and inactivated in more than 50% of PDAC." (PMID 32737864, 2021). "Mouse models have demonstrated that SMAD4 is dispensable for normal pancreas development but is critical for pancreatic cancer progression." (PMID 33669845, 2021). "Here, we report a case of stage IV pancreatic cancer in a patient with TSC2 and SMAD4 mutations treated with immunotherapy when the disease progressed after multi-line chemotherapy." (PMID 34880877, 2021). "DPC4 (for deleted in pancreatic cancer, locus 4, SMAD4) on chromosome 18q was identified as a tumor suppressor gene in pancreatic, colon, bladder, biliary tumors as well as head and neck tumors." (PMID 33450833, 2021). "This upregulation of miR-552 induced by FOXM1 further inhibited the expression of three downstream targets DACH1, PCDH10, SMAD4, which are known as tumor suppressors in pancreatic cancer progression." (PMID 33867818, 2021).
pancreatic cancer (continued). "In support of this, miRNA targeting of Smad4 in breast cancer cells attenuated autophagy whereas Smad4 depletion protected pancreatic cancer cells from radiotherapy by inducing autophagy." (PMID 34760883, 2021). "Pancreatic cancer cells with SMAD4 knockdown demonstrate increased levels of autophagy and enhanced tolerance to irradiation." (PMID 34002944, 2021). "Evidence from pancreatic cancer suggests that expression of oncogenic KRAS and loss of SMAD4 cooperate to induce the expression of EGFR and to promote invasion." (PMID 34298611, 2021). "In our study, we identified three tumor suppressor genes, DACH1, PCDH10 and SMAD4 as targets of miR-552 in pancreatic cancer." (PMID 33867818, 2021). "The SMAD4 gene (also known as deleted in pancreatic cancer locus 4 or DPC4) is located on chromosome 18q21, and is lost in roughly 55% of pancreatic cancers mainly via homozygous deletion or by intragenic mutations and the subsequent loss of heterozygosity." (PMID 34680235, 2021). "The results of the Kaplan-Miere survival analysis show that these genes are prognostically essential in pancreatic cancer.Hsa-mir-301a can promote pancreatic cancer progression by down-regulating the SMAD4 gene." (PMID 35145483, 2021). "Taken together, our findings provide a new FOXM1-miR-552-DACH1/PCDH10/SMAD4 axis to regulate pancreatic cancer cell progression and new opportunities for therapeutic intervention against this disease." (PMID 33867818, 2021). "It has been reported that SMAD4 acts as a prognostic biomarker in various human malignancies such as colorectal carcinoma and pancreatic carcinoma, but its role as a prognostic marker in breast carcinoma is still unclear." (PMID 33825073, 2021). "Smad4 is a key transcription factor in the TGF-β pathway, and malignant progression in prostate, colon and pancreatic carcinomas is associated with Smad4 loss." (PMID 34692253, 2021). "Mechanistically, SMAD4 depletion induces elevated levels of autophagy and ROS contributing to radioresistance, whereas autophagy and ROS inhibitors sensitized pancreatic cancer cells to radiation." (PMID 32651227, 2020). "Taken together, it is the first time to reveal that HEATR1, ZNF185, and SMAD4 are correlated in the chemosensitivity of gemcitabine in pancreatic cancer." (PMID 32565799, 2020). "SMAD4 also plays a role in cancer development, including colorectal liver metastases and pancreatic cancer." (PMID 33336042, 2020). "These inconsistencies might be due to an insufficient coverage of mutations within the SMAD4 gene in the panel; further technical improvement of the gene panel, which covers sufficient hot spot mutations of the SMAD4 gene, would increase the detection accuracy in patients with pancreatic cancer." (PMID 32614932, 2020). "We show that these features enable the hitherto challenging genetic modification of patient-derived cells to stably restore the tumor suppressor gene SMAD4 to a patient-derived SMAD4 knockout pancreatic cancer line." (PMID 32420409, 2020). "Restoration of SMAD4 expression in pancreatic cancer cells inhibits tumor function in vivo by influencing angiogenesis through decreased VEGF expression." (PMID 32807122, 2020).
pancreatic cancer (continued). "In pancreatic cancers, the inactivation of Smad4 significantly correlates with poor prognosis in patients with surgically resected adenocarcinoma of the pancreas." (PMID 31721429, 2020). "The tumor suppressor gene SMAD4 is mutated or deleted in 55% of PDAC and promotes pancreatic tumor progression and increases metastasis." (PMID 32651227, 2020). "Here, the authors present the evolutionary analysis of neoplastic cysts and report them as precursors of invasive pancreatic cancer, and that SMAD4/TGFBR2 alterations are likely drivers of invasion in a subset of cases." (PMID 32796935, 2020). "In approximately 30% of all pancreatic cancers, SMAD4 is homozygously deleted, and another 20% display missense, nonsense, or frameshift mutations." (PMID 32420409, 2020). "In pancreatic cancers, homozygous deletion of SMAD4 is found in approximately 30% of cases, inactivation is found in 20% of cases, and allelic loss of chromosome 18q is found in almost 90% of cases." (PMID 32429474, 2020). "For instance, RHOT1 can regulate cell migration and proliferation by suppressing the expression of SMAD4 in pancreatic cancer." (PMID 32467664, 2020). "miR-421 has been found to be upregulated in pancreatic cancer as an oncogene and potential regulator of DPC4/Smad4." (PMID 33317198, 2020). "They found that inactivation of DPC4/SMAD4 (high-frequency pancreatic cancer driver genes) sensitized pancreatic cancer cells to cisplatin." (PMID 32174830, 2020). "Mutations in other cancer-related genes, such as SMAD4, PI3KCA, PTEN, and BRAF, have been reported by previous studies in both IPMNs and pancreatic cancers with lower prevalence." (PMID 31338331, 2019). "In the present study, we showed that the expression of SMAD4 was significantly lower in pancreatic cancer tissues than in adjacent tissues by analysing 95 paraffin-embedded tissue sections of pancreatic cancer." (PMID 31684910, 2019). "Although, TGFβ-induced EMT is considered a pro-tumorigenic effect, it becomes lethal in TGFβ-sensitive (SMAD4-wildtype) pancreatic cancer by converting TGFβ-induced Sox4 from an enforcer of tumorigenesis into a promoter of apoptosis." (PMID 31569425, 2019). "For example, TIF1γ can monoubiquitinate Smad4 and suppress TGFβ signaling to inhibit the growth and invasion of pancreatic cancer cells." (PMID 31632911, 2019). "Among alterations occurring in pancreatic cancer, TGF-β signalling pathway is frequently lost as SMAD4/DPC4 (deleted in pancreatic cancer 4) is mutated in 50–80% of PDAC and mutations of TGF-βRII are also described (5–10%)." (PMID 30065235, 2018).